MMP2 (matrix metallopeptidase 2)
Diseases named in the same sentence as MMP2 in open-access papers (continued):
Sharing a sentence is not in itself a finding about the gene and the disease.
adenoma (9 papers, 2003 to 2025). A neoplasm arising from the epithelium. "In the Apcmin/+ model, supplementation with KLK1 significantly inhibited adenoma formation, reduced epithelial dysplasia, and downregulated pro‐oncogenes such as Mmp2, Mmp9, Fap, Dcn, and Ctnnb1." (PMID 40859429, 2025). "Increased KLK1 expression led to decreased Mmp2 and Mmp9 levels and reduced adenoma formation, an effect inhibited by SSR240612." (PMID 40859429, 2025). "In this study a band corresponding to active MMP-2 was observed in only two adenomas, and histological examination of these two samples showed an intense stromal reaction close to the tumor." (PMID 21726449, 2011). "Pro-MMP-9 and pro-MMP-2 were significantly concentrated in the plasma of all of the dogs, and bands for the latent forms were present in both animals with adenoma and animals with carcinoma." (PMID 21726449, 2011). "The pro-MMP-2 band was detected in all samples examined (adenoma and carcinoma)." (PMID 21726449, 2011). "In particular, significant bands were observed for both the inactive and active forms of MMP-2 in simple carcinomas, while simple adenomas were characterized by minimal bands that corresponded to pro-MMP-2, suggesting that this enzyme is important during the infiltration process." (PMID 21726449, 2011). "In this study, the immunohistochemical data for MMP-2 and MT1-MMP were comparable for both adenomas and carcinomas." (PMID 21726449, 2011). "An intense immunoreaction was especially evident for MMP-2 in carcinomas, while the difference in MMP-9 immunolabelling in adenomas and carcinomas was lower." (PMID 21726449, 2011). "On the contrary, at the protein level, immunohistochemistry identified higher MMP-2 expression in carcinomas; gelatin-zymography confirmed differences in MMP-2 production between adenomas and carcinomas (p < 0.05, data not shown)." (PMID 21726449, 2011). "The staining intensity for MMP-2 and MT1-MMP was stronger in the fibroblasts closest to the epithelial tumor cells in the malignant tumors, while the fibroblasts that were immunolabelled by the antibodies for the two proteins were scattered in the adenomas." (PMID 21726449, 2011). "In addition to MMP-7 expression, 60–65% of Min adenomas express MMP-2 and MMP-10 (stromelysin-2) and 50% express MMP-3 and MMP-13 (collagenase) with expression limited to the stroma surrounding the adenoma." (PMID 12778076, 2003). "In addition, MMP2, SNAI1, and VEGFA contributed to proliferation and invasion of adenomas." (PMID 33425722, 2020).
aortic stenosis (9 papers, 2017 to 2025). Aortic valve stenosis is a aortic valve disease caused by the incomplete opening of the aortic valve. "MMP2 degrades troponin I in IRI ischemia–reperfusion injury, while in aortic stenosis, TIMP1 and TIMP2 are related to fibrosis." (PMID 34449561, 2021). "In patients with aortic stenosis, significant sex differences were observed in genes for collagen I (COL1A1), collagen III (COL3A1), and matrix metalloproteinase 2 (MMP2), which are involved in fibrosis and inflammation regulation, with repression of these processes in women." (PMID 40136716, 2025). "For example, MMP-2 and MMP-14 levels robustly increase in LV pressure overload models and myocardial biopsies of aortic stenosis (AS), whereas the levels of MMP-14, MMP-7, MMP-8, and MMP-9 increase in end-stage dilated cardiomyopathy." (PMID 28484397, 2017).
bladder tumor (9 papers, 2004 to 2025). "Previously, we reported a novel interplay between angiogenin (ANG), a potent mediator of angiogenesis, and matrix metalloproteinase-2 (MMP2) in human bladder tumors." (PMID 27317771, 2016). "Using RT–PCR, invasive bladder tumour samples were found to have higher expression of MMP2 and TIMP2 compared to superficial tumours, and high levels of MMP2, TIMP2 and MT1-MMP were associated with decreased patient survival." (PMID 15083203, 2004). "We establish a new bridge between XIAP overexpression and MMP2 activation in human BC high invasion, and further help us better understand XIAP induction associated with the progression and the aggression of malignant bladder tumor development." (PMID 31811115, 2019). "Taken together, we suspected that CD164 could promote the migration and invasion of bladder tumor cells through regulating relevant proteins including MMP2 and MMP9." (PMID 30022623, 2018). "Furthermore, TRPV2 activity, which may be mediated by direct MMP2 regulation, is important in bladder tumor development and progression." (PMID 24223658, 2013). "This study showed that MMP2, MT1-MMP, and MMP28 were very highly expressed in bladder tumour samples and MMP1, 7, 9, 11, 15, 19, and 23 were also highly expressed." (PMID 16901349, 2006). "In this study we will focus on MMPs, which are described in the literature to have an impact in bladder tumour carcinogenesis: the collagenase MMP1, the stromelysin MMP3, and the gelatinases MMP2 and MMP9." (PMID 16901349, 2006). "Thus, the overall, high expression of MMP-2, RB and/or PAI-1 in bladder tumors was a marker of poor prognosis." (PMID 29245935, 2017). "Thus, overall, high expressions of MMP-2, RB and/or PAI-1 in bladder tumors were markers of poor prognosis." (PMID 29245935, 2017). "TRPV2 activity, which may be mediated by direct matrix metalloproteinase 2 (MMP2) regulation, is important in bladder tumor development and progression." (PMID 24223658, 2013). "The authors concluded that MMP2 and TIMP2 contribute to bladder tumour invasiveness and therefore might be useful prognostic markers in the future." (PMID 16901349, 2006).
Chagas disease (9 papers, 2017 to 2025). A parasitic infection caused by Trypanosoma cruzi. "In human Chagas disease, MMP-2 has been previously associated with regulatory responses in IND patients by correlations with regulatory cytokines, especially IL-10, whereas MMP-9 has been associated with inflammatory response and cardiomyopathy." (PMID 31578449, 2019). "Particularly in Chagas Disease, neutrophils and monocytes show differential expression of MMP-2 and MMP-9 in the bloodstream." (PMID 33891967, 2021). "In Chagas disease, circulating MMP-2 and -9 were proposed as biomarkers for asymptomatic to cardiac form progression, and alterations in their activity and expression during T. cruzi acute experimental infection have also been observed." (PMID 33891967, 2021). "Due this dichotomous characteristic in the activation of IL-1β in patients with different clinical forms of Chagas' disease, we propose MMP-2 and MMP-9 as potential biomarkers of prognostic which should be better investigated." (PMID 31057540, 2019). "Furthermore, in comparison with controls, the increased levels of MMP-2 in our study are similar to that found in non-Chagas disease patients with HFREF." (PMID 37122872, 2023). "used multiplex analysis of serum samples (participants classified by the New York Heart Association) to show that the MMP-2/MMP-9 ratio increased with the severity of cardiac disease, where patients with severe cardiac Chagas disease presented with increased levels of MMP‐9 compared with MMP‐2." (PMID 35895410, 2022). "In Chagas disease patients, T cells, neutrophils and monocytes are source of MMP-2 and MMP-9." (PMID 29375564, 2017). "Here, we characterize the MMP-2 and MMP-9 gelatinases as putative biomarkers of the evolution of clinical forms in Chagas disease." (PMID 31578449, 2019). "In conclusion, our results point out that MMP-2 and MMP-9 together could be a tool for predicting clinical evolution in Chagas disease." (PMID 31578449, 2019). "We have pointed out that MMP-2 and MMP-9 together can predict clinical evolution in Chagas disease." (PMID 31578449, 2019). "In vitro stimulation with T. cruzi-derived antigens induces higher MMP-2 and MMP-9 expression in monocyte from patients with cardiac clinical forms of Chagas disease compared with those from non-infected patients." (PMID 29375564, 2017).
epilepsy (9 papers, 2011 to 2024). A brain disorder characterized by episodes of abnormally increased neuronal discharge resulting in transient episodes of sensory or motor neurological dysfunction, or psychic dysfunction. "In this study, we reported that Gb and Ocs extracts attenuated brain edema and BBB damage by restoring tight junction proteins and MMP-2 in a PTZ-induced animal model of epilepsy." (PMID 37695764, 2023). "A set of molecules associated with BBB permeability (MMP-2, MMP-9, S100B), restoration (TIMP-1, TIMP-2, TSP-2), neuroinflammation (CCL-2), and endothelial activation (ICAM-1, P-sel) that are affected in epilepsy and can be measured in blood was selected in this study." (PMID 36766708, 2023). "In our study, serum MMP-2 level was higher in patients with epilepsy." (PMID 36766708, 2023). "The molecules whose levels are chronically elevated in serum of patients with epilepsy (MMP-2, MMP-9, S100B, TIMP-1, TIMP-2) might be considered diagnostic biomarkers of epilepsy." (PMID 36766708, 2023). "MMP-2 may increase the permeability of the blood–brain barrier which encourage seizures appearance and facilitates epilepsy development." (PMID 31172215, 2019). "We showed that serum levels of molecules associated with BBB disruption (MMP-2, MMP-9, S100B) and restoration (TIMP-1, TIMP-2) are increased in patients with epilepsy in the interictal period, which might reflect chronic processes taking place at the BBB, even in the absence of seizures." (PMID 36766708, 2023). "Interestingly, MMP-2 serum levels in patients with epilepsy were significantly lower." (PMID 31172215, 2019). "Previous studies using the rat pilocarpine model of TLE have reported downregulation of tight junction proteins and upregulation of matrix metalloproteinases Mmp2 and Mmp9 in brain capillary tissue after 48 h, leading to BBB dysfunction in epilepsy." (PMID 39040630, 2024). "Serum levels of MMP-9, MMP-2, TIMP-1, TIMP-2 and S100B were higher in patients with epilepsy in comparison to control group (p < 0.0001; <0.0001; 0.001; <0.0001; <0.0001, respectively)." (PMID 36766708, 2023). "Serum levels of MMP-9, MMP-2, TIMP-1, TIMP-2 and S100B are elevated in patients with epilepsy in the interictal period, which suggests chronic processes of BBB disruption and restoration." (PMID 36766708, 2023). "Serum levels of MMP-9, MMP-2, TIMP-1, TIMP-2, S100B, CCL-2, ICAM-1, P-selectin, and TSP-2 were examined in a group of 49 patients with epilepsy who were seizure-free for a minimum of seven days and measured by ELISA." (PMID 36499038, 2022). "Expression of MMP-2 and MMP-9 increases in the brain of patients with epilepsy, and serum levels of MMP-9 are elevated after seizures." (PMID 36499038, 2022). "In patients with epilepsy examined regardless of the time from last seizure, the serum level of MMP-2 was lower than in control group." (PMID 36766708, 2023). "However, in several studies, lower MMP2 and MMP3 serum levels were reported in epilepsy patients as compared to control." (PMID 36289737, 2022). "However, the serum level of MMP-2 after seizures was not significantly increased, and in a population of epilepsy patients with a mean time of remission of 164 days, it was lower than in controls." (PMID 36499038, 2022). "However, as so far, there is no further data describing the involvement of MMP-2 in epilepsy development." (PMID 31172215, 2019). "The lack of correlation between serum level of TIMP-2 and MMP-2/TIMP-2 ratio might result from constitutive expression of TIMP-2 and less pronounced differences between the serum TIMP-2 levels in patients with epilepsy and control group." (PMID 36766708, 2023). "Recently, IPR-179 (Act-03), a novel MMP2/MMP9-selective inhibitor, has been developed, which has antiseizure as well as antiepileptogenic effects and attenuates seizure-induced cognitive decline, without severe side effects, in two rodent models of epilepsy." (PMID 36289737, 2022).
gallbladder cancer (9 papers, 2013 to 2025). "Inhibition of gallbladder cancer cell invasiveness functions via the suppression of matrix metalloproteinase-2 (MMP-2) and MMP-9 and epithelial-mesenchymal transition." (PMID 31979397, 2020). "It has been reported that NCTD decreased the ratio of MMP2 to TIMP2 and reduced cellular mortality, exerting anti-invasive activity in human gallbladder carcinoma cells." (PMID 23825538, 2013).
Hernia (9 papers, 2006 to 2025). "Thus a study was planned with research objectives to establish a causal association between hernia and MMP-2 and to test the hypothesis that hernia is a local manifestation of a systemic disorder rather than a mere local mechanical defect." (PMID 22481991, 2009). "Conversely, direct hernia fascia shows decreased TIMP-2 immunostaining compared to controls and indirect hernia, a shift that would favor sustained MMP-2 activation and collagen loss." (PMID 41440470, 2025). "Our results concerning MMP-2 are not in agreement with those reported in previous studies showing higher MMP-2 serum levels in hernia patients." (PMID 40806165, 2025). "Various studies consistently indicated an increase in MMP-2 in the serum and/or tissue levels of hernia patients, especially those having direct, recurrent, or bilateral hernia." (PMID 40806165, 2025). "The overexpression of PI16 inhibits MMP activity, and MMPs, including MMP1, MMP2, MMP9, and MMP13, are associated with abdominal hernia development." (PMID 34341761, 2021). "Both MMP-2 enzyme activity and mRNA expression were similar in hernia and control fibroblasts in vitro." (PMID 22481991, 2009). "Statistically, serum levels of MMP-2 were significantly increased in all the hernia patients as compared to controls." (PMID 22481991, 2009). "Similar up-regulation of active MMP-2 with relative reduction in TIMP-2 is detectable in abdominal skin fibroblasts from hernia patients, consistent with a broader connective-tissue susceptibility beyond the hernia margin." (PMID 41440470, 2025). "Based on above facts, a hypothesis was generated that hernia is a local manifestation of a systemic disease which is manifested by increased expression of MMP-2." (PMID 22481991, 2009). "MMP-2 was found to be abnormally high at both mRNA and protein levels in serum and fascial tissues of patients with ventral wall hernias; some studies showed that MMP-9 expression was increased in the hernia-positive group." (PMID 38591204, 2024). "Because there is statistically significant increase in serum MMP-2 levels in patients of indirect and direct hernia both as compared to controls, thus we can conclude that hernia is not a mere local defect but a local manifestation of a systemic disease." (PMID 22481991, 2009). "However, MMP-2 concentrations appeared lower in patients with familial history of hernia compared to those without." (PMID 40806165, 2025). "Though our in vitro study presents preliminary results, the coherence of MMP-2 inhibition and diminished type IA1 to III collagen ratio in incisional hernia fibroblasts approves that the expression and processing of key molecules in wound healing is disturbed in hernia patients." (PMID 17010202, 2006). "Based on this finding, we compared both zymographic MMP-2 activity and MMP-2 concentration measured by immunoassay in controls and patients without familial history of hernia, but no variations emerged." (PMID 40806165, 2025).
inflammatory bowel disease (9 papers, 2011 to 2025). A spectrum of small and large bowel inflammatory diseases of unknown etiology. "The study also aimed at evaluating the association of intestinal mucosal MMP-2 and -9 activities with histological changes, the canine inflammatory bowel disease activity index (CIBDAI), the clinical outcome, and hypoalbuminemia in dogs with CE." (PMID 29530095, 2018). "Mucosal MMP-2 and -9 activities have been reported to be upregulated in the intestine of humans with inflammatory bowel disease (IBD), and in animal models of IBD." (PMID 29530095, 2018). "In previous studies we demonstrated enhanced expression of tumor-associated MMPs (MMP-2, MMP-7, MMP-9, and MMP-13) in native, unfixed, but cryo-conserved samples of patients with inflammatory bowel disease by qRT-PCR, ELISA, and immunofluorescence." (PMID 27716617, 2016). "Decreased MMP-2 expression was observed in inflammatory bowel disease (IBD) patients and was hypothesized to deregulate the intestinal barrier and stimulate fibrosis." (PMID 38338780, 2024). "In the research and analysis of the correlation between the destruction of ECM and inflammatory bowel disease, it was found that the expression of MMP-2 and MMP-9 in the tissues of patients with inflammatory bowel disease was significantly higher than that of the control group." (PMID 34327245, 2021). "Previous research on celiac disease and inflammatory bowel disease had reported similar imbalances, with elevated MMP-1 and MMP-2 and decreased TIMP-1 and -2 levels in the gut." (PMID 40524059, 2025).
keratoconus (9 papers, 2013 to 2025). A degenerative, structural disorder of the eye, characterized by a cone-shaped protrusion of the cornea. "Multiple studies do show a consistent relative decrease in TIMP levels, including TIMP-2, compared to MMP-2 levels in corneas and keratocyte cultures derived from keratoconus patients, suggesting upregulated MMP-2 plays a role in keratoconus." (PMID 39883547, 2025). "MMP-2 has been thoroughly investigated in keratoconus, where its levels were found to be upregulated, unaltered, or downregulated." (PMID 39883547, 2025). "–56 This relationship suggests that WST-D/NIR treatment might have a targeted effect on the pathways involved in keratoconus, by reversing the dysregulation of MMP-2 in keratoconus by the upregulation of TIMP-2." (PMID 39883547, 2025). "In this study, thirty-two FDA-approved ophthalmic drugs were exposed to virtual screening using docking studies against both the MMP-2 and MMP-9 proteins to find the most promising inhibitors as a proposed computational mechanism to treat keratoconus." (PMID 35684529, 2022). "MMP-2 and MT1-MMP (MMP-14) protein is expressed in multiple layers of the normal and keratoconus human CE, with MT1-MMP appearing mostly in the basal layer and MMP-2 more diffuse throughout the CE." (PMID 25412440, 2014).
papillary thyroid cancer (9 papers, 2008 to 2021). "MKL1 recruits Smad3 to transactivate MMP2 in papillary thyroid cancer, consequently accelerating nodal metastasis." (PMID 33500406, 2021). "The study of co-expression of bone sialoprotein, integrin αVβ3, and MMP-2 in papillary thyroid carcinoma cells demonstrated that cancer cells appear to become more invasive when bone sialoprotein forms a cell-surface trimolecular complex that links MMP-2 to integrin αVβ3." (PMID 19787098, 2008). "Of note, among the downregulated genes MMP2, VEGFA, CCND1, and TWIST1 were downregulated only in papillary carcinoma but were either unchanged or upregulated in other two subtypes." (PMID 30863721, 2019). "In the current investigation, we aimed to evaluate the synergistic effects of celecoxib (CX) and sodium valproate (VPA) against cell survival, invasiveness properties, and expression of metalloproteinase-2 and -9 (MMP-2 and MMP-9) in papillary thyroid cancer cell line, B-CPAP cells." (PMID 30127823, 2018). "Furthermore, a reduction in the expression and activity of MMP-2 and MMP-9 could be possible by applying a non-atmospheric plasma on thyroid papillary cancer cells." (PMID 33799923, 2021).